IGF1R (insulin like growth factor 1 receptor)
Diseases named in the same sentence as IGF1R in open-access papers (continued):
Sharing a sentence is not in itself a finding about the gene and the disease.
osteosarcoma (continued). "Furthermore, a review of the literature suggests that KIT, PDGFRs, MET, IGF‐1R, and AXL could also serve as potential therapeutic targets for osteosarcoma." (PMID 40344484, 2025). "Additionally, a Phase 1/2 clinical trial (NCT03746431) targeting IGF1R-overexpressing solid tumors with a radioimmunotherapeutic agent ([225Ac]-FPI-1434) is ongoing, which could prove to be promising for osteosarcoma treatment." (PMID 35887382, 2022). "However, upon examination, the trial included only 11 osteosarcoma cases, of which only two cases showed strong immunohistochemistry expression of IGF1R, and no evaluation of IGF1R copy number was used to guide treatment." (PMID 35887382, 2022). "Notably, targeting IGF-1R-with figitumumab (CP751871) resulted in attenuated IGF-1R signaling correlated with a significant downregulation of VEGF in several sarcoma xenografts, including osteosarcoma and EWS." (PMID 34069554, 2021). "A bispecific antibody targeting IGF-1R and EGFR was able to inhibit tumour growth and prevent lung metastases in a mouse osteosarcoma model, suggesting that it may have potential as a therapy for metastatic osteosarcoma, though this has yet to be tested clinically." (PMID 32961800, 2020). "In addition, we reviewed the literature and found that MET, IGF-1R, and AXL may also be relevant targets for the treatment of osteosarcoma." (PMID 32984034, 2020). "However, despite encouraging preclinical data, clinical trials of IGF-1R inhibitors for osteosarcoma have not yielded satisfactory results." (PMID 32984034, 2020). "In general, IGF-1R might be one of the drivers of osteosarcoma, but inhibiting it alone is clearly not an option." (PMID 32984034, 2020). "IGF-1R inhibitors should be tested in combination with chemotherapeutic agents, as it has been described that the ligand IGF-2 is upregulated in patients in response to chemotherapy and that in osteosarcoma cell lines IGF-1R inhibition can enhance the effect of doxorubicin and radiotherapy." (PMID 26563243, 2016). "In addition, miR-194 specifically downregulated the expression of IGF1R and CDH2. miR-194 gene therapy may prove to be a promising therapy for tumorsuppression in osteosarcoma." (PMID 25096247, 2014). "Thus, the anti-IGF1R-Actinium-225 strategy may be another way to treat osteosarcoma metastases that are not osteoblastic and with alpha-particle radiation that effectively acts at short distances in a powerful manner." (PMID 36457575, 2022). "Thus, IGF1R and tyrosine kinase-like orphan receptor 1 (ROR1) CAR-T cells obtained from sarcoma patients could secrete Inf-γ and pronouncedly attenuate tumor growth in systemically disseminated and localized osteosarcoma xenograft mouse models." (PMID 34069554, 2021). "Further, we show that high nuclear-phosphorylated IGF-1R and low YAP N:C ratio are potentially negative prognostic indicators for overall survival in osteosarcoma." (PMID 35284040, 2022). "Nuclear IGF-1R intensity and TAZ N:C ratios were not statistically different across the tumors with different predominant histotypes present in the osteosarcoma biopsies." (PMID 35284040, 2022). "Indeed, total IGF-1R expression level was not predictive of a response to R1507 in our cell lines, as previously reported for a different anti-IGF-1R antibody (h7C10, Merck) in rhabdomyosarcoma and R1507 and AMG479 in osteosarcoma." (PMID 22022506, 2011).
Insulin resistance (114 papers, 2009 to 2025). Increased resistance towards insulin, that is, diminished effectiveness of insulin in reducing blood glucose levels. "HepG2 IGF1R KO cells exposed to long-term pathological insulin concentrations exhibited the hallmark characteristics of insulin resistance, such as decreased levels of AKT phosphorylation upon 5-minute insulin stimulation." (PMID 39572596, 2024). "Another study showed that the loss of one allele of IGF1R is associated with glucose intolerance and later insulin resistance, resulting in low birth weight and growth." (PMID 38274107, 2023). "The zMIR fish expresses dominant-negative Igf1r in skeletal muscle, which causes insulin resistance." (PMID 36001973, 2022). "IGF-1R can form hybrid receptors with insulin receptor (IR), and insulin resistance is one of risk factors of neurodegenerative diseases." (PMID 34445359, 2021). "Mice with one of the Igf1r alleles deficient (Igf1r±) globally exhibited a 10% decrease in post-natal growth, and developed glucose intolerance and insulin resistance with age." (PMID 34527673, 2021). "Heterozygous deficiency of Igf1r reduced postnatal growth and develop age-dependent insulin resistance." (PMID 29996846, 2018). "The possible reason is that IGF-1R is associated with insulin resistance in mature adipocytes, which accounted for approximately 80% in adipose tissue." (PMID 29721149, 2018). "Among these metabolic disorders, activation of the IGF/IGF-1R axis, which is caused by insulin resistance and hyperinsulinemia, is considered to play a key role in liver carcinogenesis in patients with metabolic syndrome." (PMID 25789501, 2015). "Alterations in the IGF/IGF-1R axis caused by insulin resistance contribute to the development of CRC." (PMID 22312273, 2012). "The IGF-1R-induced accumulation of orbital fat in TAO may underlie insulin resistance, representing a potential molecular mechanism." (PMID 39135625, 2024). "Indeed, e.g., an age-associated cholesterol reduction triggers brain insulin resistance by facilitating ligand-independent receptor activation, while activation of InsR and IGF1R depends critically on the structures of membrane sterols." (PMID 36835322, 2023). "Also, male mice carrying a genetic mutation that lack one of the Igf1r alleles (Igf1r+/−) were glucose intolerant and both males and females developed insulin resistance as they age." (PMID 36353242, 2022). "Insulin resistance, as a pathogenic base of glucose metabolism abnormalities, affects the action of sex hormones on the ovaries and endometrium through insulin-like growth factor-1 receptor (IGF-1R), leading to anovulation or endometrial lesions." (PMID 36714308, 2022). "Insulin resistance is associated with the insulin like growth factor 1 receptor (IGF-1R)." (PMID 36465658, 2022). "Furthermore, UBIKOR IGF1R-deficient mice that were generated using the same genetic strategy than our CreERT2 mice also developed a mild glucose intolerance and insulin resistance." (PMID 36353242, 2022). "Indeed, in spite of lack of activity against the IR, some mAbs induce ligand-independent internalization and degradation of IGF1R/IR-A and IGF1R/IR-B hybrids, causing insulin resistance." (PMID 34440844, 2021). "This may be, in part, due to increased rates of obesity in African American women, which is often associated with insulin resistance and dysfunction of IGF-1R." (PMID 35008602, 2021). "Moreover, let-7 has been shown to be directly involved in glucose metabolism and insulin resistance acting on targets associated with the insulin/IGF-1R pathway in mice." (PMID 28974990, 2017). "Also, mice carrying a genetic mutation that lack one of the igf1r alleles (igf1r+/−) show a 10 % reduction in post-natal growth, insulin resistance and glucose intolerance." (PMID 26733412, 2016).
Insulin resistance (continued). "Additionally, hyperinsulinemia caused by insulin resistance could promote cancer cell mitosis through molecules such as insulin receptor-A and insulin-like growth factor-1, or through activation of the insulin-like growth factor-1 receptor signaling pathway." (PMID 34604147, 2021). "miR-122 was consistently elevated and strongly linked to hepatic insulin resistance, regulating AKT3 and IGF1R." (PMID 41400625, 2025). "Cavity protein-1 (cav-1), a protein that coexists with insulin-like growth factor receptor (IGF1R) and insulin resistance (IR), stimulates IGF1R/IR and glycolysis in cancer cells and triggers a malignant state in tumor carriers." (PMID 40630951, 2025). "The overexpression of kinase-dead insulin receptor (IR) or IGF-1 receptor (IGF1R) in muscle leads to glucose intolerance, high levels of circulating triglycerides, and insulin resistance in mice." (PMID 40141045, 2025). "Many papers have investigated the role of Insulin-Like Growth Factor 1 Receptor (IGF-1R) and the mTOR genes in insulin resistance and mTOR pathway in T2DM." (PMID 40533788, 2025). "In mHypoE-46 neurons, treatment with 10nM insulin for 6 hours, which is prior to the development of cellular insulin resistance, still resulted in significant downregulation of Igf1r, Irs1, and Irs2." (PMID 40105689, 2025). "Aging neurons are accompanied by an increase in insulin resistance and a decrease in sensitivity to IR, such as IR and IGF‐1R, resulting in inefficient glucose utilization." (PMID 41395450, 2025). "IGF1R which is a tyrosine kinase, plays a vital role in insulin signaling leading to insulin resistance." (PMID 40533788, 2025). "Because insulin resistance involves the dysregulation of multiple growth factor signals, including IGF-1R, miRNAs affecting IR sensitivity are also likely to impact the IGF-1R pathway." (PMID 38540176, 2024). "Growth hormone elevation, subsequent to the IGF-1R antibody, resulted in hyperglycemia and metabolic syndrome due to insulin resistance." (PMID 39273251, 2024). "These initial experiments confirmed that the HepG2 IGF1R KO cell model displayed the expected traits of insulin resistance, thus making it a suitable model for the analyses of hepatocellular insulin resistance." (PMID 39572596, 2024). "In contrast, metformin, which counteracts insulin resistance, can reduce the risk by activating AMPK and inhibiting IGF‐1R, respectively." (PMID 38751364, 2024). "Multiple serine phosphorylation by different kinases abrogates IRS1 binding to IGF1R and interrupts downstream activation of pro-proliferative signaling leading to insulin resistance." (PMID 39682211, 2024). "Another study suggested that the development, proliferation, and survival of pancreatic β-cells, as well as the β-cell compensation for peripheral insulin resistance, are mediated by the IGF-1R signalling pathway through IRS-2." (PMID 37569816, 2023). "Studies have demonstrated that activation of IGF-1R induces Tregs and that insulin resistance correlates with decreased Tregs." (PMID 37361575, 2023). "Insulin resistance can stimulate cell proliferation and inhibit apoptosis, thus contributing to tumor promotion and metastasis through signal transduction of the insulin-like growth factor-1 receptor pathway." (PMID 36209108, 2022). "MiR-122 elevation has been found to aggravate insulin resistance in hepatocytes by targeting insulin-like growth factor 1 receptor (Igf-1r), indicating that it has a possible contribution to the progression of atherosclerosis in T2D." (PMID 36286043, 2022). "Disruption of IGF1R signaling in mice has led to some degree of glucose intolerance and insulin resistance in most models examined including ours." (PMID 36353242, 2022). "Other models of IGF1R or InsR/IGFIR double-knockout in brown adipose tissue also revealed insulin resistance." (PMID 36353242, 2022). "High-fat-diet-induced insulin resistance and glucose intolerance have been observed in gender-specific IGF-1R heterozygous mice." (PMID 35840554, 2022).
Insulin resistance (continued). "There was a highly significant positive correlation between each of the following: LncRNA-RP11-773H22.4, RET, IGF1R, mTOR mRNAs, glycemic control and insulin resistance." (PMID 34360895, 2021). "In summary, the relationship between H19/IGF-1R and insulin resistance is currently inconsistent in the literature, which warrants further investigation." (PMID 31847392, 2019). "Collectively, this review demonstrates that ncRNAs involved in IGF-1R signaling, directly or indirectly, plays an important role in linking insulin resistance to DM and cancer." (PMID 31847392, 2019). "With regard to the IGF-1 receptor, the increased levels of IGF-1R protein and tyrosine phosphorylated IGF-1R suggest that signaling through IGF-1R pathways was increased, perhaps as a compensatory response to insulin resistance." (PMID 26322248, 2012). "Furthermore, heterozygosity for Igf1r is reported to promote insulin resistance in mice, though effects appear to be most pronounced in males." (PMID 41402425, 2025). "Since there is increasing evidence of the association between insulin resistance and neurodegenerative disease, the role of IGF-II, which has a higher affinity than IGF-I for IRA/IGF1R hybrids and interacts with IGF2R, including its soluble form, is recommended as a research focus." (PMID 38674097, 2024). "Another mechanism linking IGF1R rs6598541 to urate levels is insulin resistance." (PMID 38347000, 2024). "Additionally, it has been discovered that silencing Klotho in high glucose-treated cells increased IGF1R, p-IGF1R and IGF1 expression, and activates the IGF1/PI3K/Akt/mTOR signalling pathway, known to be associated with insulin resistance." (PMID 38486352, 2024). "Insulin resistance is closely related to the insulin-like growth factor 1 receptor (IGF-1R)." (PMID 39135625, 2024). "During the period of prediabetes, the interference of IGF1R signaling in fat tissue may result in insulin resistance and progression to T2DM." (PMID 36891946, 2023). "Studies have also revealed that insulin resistance induction can lead to augmented expression of pancreatic β-cell senescent markers, including a high expression level of SA-β-Gal, p16 INK4a, p53BP1, and IGF-1R." (PMID 37868908, 2023). "Taken together, enhanced adipogenesis activated by IGF-1R leading to insulin resistance could be the potential molecular mechanism in TAO." (PMID 36465658, 2022). "Some inhibitors block the pathways that are also involved in glucose regulation, such as the tyrosine kinase receptors insulin growth factor receptor 1 (IGF-1R) which could lead to insulin resistance." (PMID 35406580, 2022). "Also, both markers were found to be related with acanthosis nigricans, which is one of the clinical manifestations of insulin resistance, due to the presence of keratinocytes and fibroblasts able to respond to insulin through the expression of IGF1-R." (PMID 36213269, 2022). "Further studies are required to investigate whether ALM extract or its pure compounds protect against the development of insulin resistance by increasing IGF1R activity or whether it exerts direct inhibitory effect on INSR is involved." (PMID 34483915, 2021). "In addition, insulin-like growth factor 1 (IGF1) / insulin-like growth factor 1 receptor (IGF1R) signaling pathway has been demonstrated to be essential for the process of insulin resistance, which leading to metabolic diseases and type 2 diabetes." (PMID 34527673, 2021). "Alternatively, this diet may affect Igf1r (IGF-I receptor gene) expression in the blastocysts, resulting in subsequent insulin resistance." (PMID 29570689, 2018). "Moreover, miRNAs of this family regulate glucose metabolism and peripheral insulin resistance by targeting IGF1R, insulin receptor (INSR), and insulin receptor substrate-2." (PMID 28974990, 2017).
Insulin resistance (continued). "What's more, obese women may suffer from insulin resistance, and concurrent hyperinsulinemia with excess insulin-like growth factor-1 receptor (IGF-1) could additionally induce androgen steroidogenesis and lead to tumor development." (PMID 27119509, 2016). "Next, we examined the role of IGF1R on HUA induces insulin resistance in H9c2 cells." (PMID 26836389, 2016). "We examined whether HUA induces insulin resistance are insulin receptor-mediated or can be ascribed to activation of the IGF1R in H9c2 cells." (PMID 26836389, 2016). "Although the diabetic MKR mice were generated by overexpression of a dominant-negative human IGF-1R in skeletal muscle, it has previously been found that these mice also develop insulin resistance in liver and adipose tissue as well as a decrease in adipose tissue mass." (PMID 25784953, 2015). "While the mechanisms are yet to be investigated, insulin resistance with secondary hyperinsulinemia is the most frequently proposed hypothesis, as insulin may have a possible mitogenic effect via its binding to the insulin-like growth factor-1 receptor." (PMID 22448244, 2012). "While IGF1 receptor (IGF1R) is exclusively down-regulated, decreased IGF1R signaling pathway may partially explain the insulin resistance after 8 weeks of age in GK rats." (PMID 21689475, 2011). "Furthermore, insulin resistance promotes overproduction of insulin-like growth factor-1, which, upon binding to IGF-1R, activates mitogen-activated protein kinase and phosphatidylinositol 3 kinase signaling pathways that enhance the genesis and metastasis of ocular melanoma tumors." (PMID 40862816, 2025). "However, the implications of increased EphA2 levels in the HepG2 IGF1R KO cell model with induced insulin resistance remain unknown." (PMID 39572596, 2024). "In 2017, Aguayo Mazzucato’s experiments demonstrated that insulin resistance in insulin-resistant mouse models could increase the expression level of senescent markers of pancreatic β-cells, such as p16INK4a, IGF-1R, and BAMBI, thereby accelerating the senescence of pancreatic β-cells." (PMID 37868908, 2023). "Interestingly, IGF1R deficiency in males but not in females resulted in resistance to aging- or HFD-induced insulin resistance and increased adiposity, in opposition to previous studies." (PMID 36353242, 2022). "However, to the best of our knowledge, there is no study examining its association with insulin resistance and tissue levels of insulin-like growth factor 1 receptor (IGF-1R) and insulin-like growth factor 2 receptor (IGF-2R)." (PMID 33143702, 2020). "Together with a potential direct action of fenugreek compounds, the rise in plasma insulin under lactation-specific conditions, i.e., hypo-insulinemia and insulin-resistance in peripheral tissues except mammary gland, could explain the Igf1r, Insr and Ghr overexpression in the mammary gland." (PMID 33081164, 2020). "Furthermore, rats infused with aldosterone also develop systemic and vascular insulin resistance, effects that might be related to increased levels of insulin-like growth factor-1 receptor (IGF-1R) and to hybridization of IGF-1R and IR." (PMID 25352918, 2014). "Compensatory hyperinsulinemia from insulin resistance reduces hepatic IGF binding protein production, increasing bioavailable IGF-1 that stimulates IGF-1R signaling pathways promoting cellular growth and metastatic spread." (PMID 41561157, 2025). "The HepG2 IGF1R KO and WT cell models exhibited decreased metabolic AKT signaling during insulin resistance." (PMID 39572596, 2024). "In conclusion, our findings indicate that insulin induces insulin resistance in human DPSCs, resulting in impairments in proximal insulin signaling events (INSR, IGF1R, IRS1, and PI3K) while maintaining the activity of distal pathway components (AKT and mTOR)." (PMID 39075596, 2024).